DKK3 (dickkopf Wnt signaling pathway inhibitor 3)
Diseases named in the same sentence as DKK3 in open-access papers (continued):
Sharing a sentence is not in itself a finding about the gene and the disease.
prostate carcinoma (continued). "The results of our WPMY-1 cell experiments indicate that stromal Dkk-3 can attenuate prostate epithelial cell proliferation, restore normal prostate epithelial architecture (as reflected by the acinar morphogenesis assays) and inhibit prostate cancer cell invasion." (PMID 29858602, 2018). "However to our knowledge, there have been no reports regarding DKK3 gene polymorphisms in prostate cancer." (PMID 26689513, 2015). "Likewise to WIF1, the DKK3 gene was also reported as a frequent target of epigenetic inactivation in numerous tumor entities, e.g. in lung cancer, prostate cancer and leukemia, suggesting that DKK3 may exert tumor suppressive functions." (PMID 19570204, 2009). "Moreover, DKK3 depletion in WPMY-1 prostate stromal cells is reported to increase TGF-β signaling activity and extracellular matrix protein 1 (ECM-1) secretion, and stromal cell-conditioned media from DKK3-deficient WPMY-1 cells was found to inhibit prostate cancer cell invasion." (PMID 36671452, 2022). "It has been reported that the over-expression of REIC/DKK3 in cancer cells can induce apoptosis, and there are clinical trials of REIC/DKK3 gene therapy for prostate cancer, liver cancer, and endometrial cancer." (PMID 36376957, 2022). "The inhibitory effects of Dkk-3 on tumor cell proliferation have been exploited in adenoviral therapies (Ad-REIC), where promising results have been observed in prostate cancer patients." (PMID 36497305, 2022). "Recently, Dkk-3 was reported to modulate the response to TGF-β, which promotes the differentiation of fibroblasts into CAFs in prostate cancer." (PMID 36497305, 2022). "By targeting Dickkopf WNT signaling pathway inhibitor 3 (DKK3), miR-1303 is known to activate Wnt/β-catenin signaling and facilitate prostate cancer progression by regulating proliferation, migration, and invasion." (PMID 33435156, 2021). "Here we explore the functional relationships between LINC00261, DKK3, and GATA6 as well as their roles in prostate cancer in order to uncover a promising strategy for prostate cancer treatment." (PMID 33013201, 2020). "Given the effect of CRISPR induction of DKK3 on TGF-β-dependent transcriptional activity, we wished to determine if it also had an impact on TGF-β-dependent prostate cancer cell migration." (PMID 29843383, 2018). "Here we show that DKK3 silencing in WPMY-1 prostate stromal cells increases TGF-β signaling activity and that stromal cell-conditioned media inhibit prostate cancer cell invasion in a Dkk-3-dependent manner." (PMID 29858602, 2018). "Dkk-3 is also expressed in prostate stroma, with increased levels reported in benign prostatic hyperplasia (BPH) and prostate cancer." (PMID 29858602, 2018). "To evaluate the interaction between canine REIC/Dkk-3 and SGTA in the AR signal transduction pathway in canine prostate cancer, we first measured the extent of AR signalling activation by the probasin promoter-driven luciferase reporter assay." (PMID 28599655, 2017). "This study aimed to assess the effects of REIC/Dkk-3 and SGTA interactions on AR signalling in the canine androgen-independent prostate cancer cell line CHP-1." (PMID 28599655, 2017). "The expression of both REIC/DKK-3 and SGTA proteins was observed in human Hs68 fibroblasts; however, only SGTA expression was detected in 293T cells and in PC3 human prostate cancer cells." (PMID 26658102, 2016). "To examine the roles of intracellular SGTA and REIC/DKK-3 and their interaction in AR signal transduction, we expressed and co-expressed these proteins in PC3 prostate cancer cells under additional AR co-expression." (PMID 26658102, 2016). "DKK3 promotes fibroblast proliferation and myofibroblast differentiation and represents a potential therapeutic target for stromal remodeling in BPH and prostate cancer." (PMID 26689513, 2015).
prostate carcinoma (continued). "In fact, gene therapies delivering DKK3 and AXIN2, which were demonstrated to be targets of miR-582-3p in this study, are being clinically tested in prostate cancer and colon cancer, respectively (NCT01197209, NCT01882660)." (PMID 26468775, 2015). "Expression patterns of the secreted glycoprotein Dickkopf-related protein 3 (Dkk-3) are altered in benign prostatic hyperplasia (BPH) and prostate cancer (PCa)." (PMID 23765731, 2013). "The down-regulated expression of DKK3/REIC in osteosarcoma, hepatoblastma and prostate cancer further supports this notion." (PMID 19247449, 2009). "High levels of stromal DKK-3 in benign prostatic hyperplasia (BPH) and prostate cancer (PCa) have been reported to increase fibroblast proliferation, promote myofibroblast differentiation, and contribute to the angiogenic switch by suppressing vessel-stabilizing factors like angiopoietin-1 (ANGPT1)." (PMID 38201279, 2023). "Similarly, DKK3 (also known as REIC, reduced expression in immortalized cells) gene amplification and homozygous deletion are also infrequent events in prostate cancer (0.2–1.5% and 0.2–0.6% incidence, respectively)." (PMID 35204808, 2022). "In prostate cancer, the overexpression of LINC00261 was shown to inhibit the transcription of dickkopf-related protein 3 (DKK3) by recruiting GATA binding protein 6 (GATA6), resulting in the inhibition of tumor angiogenesis; this action was reversed by silencing DKK3." (PMID 34022894, 2021). "Additionally, several direct targets of miR-183 have also been proposed, such as ezrin in lung cancer cells, together with Dkk-3 and SMAD4 in prostate cancer cells." (PMID 31210063, 2019). "However, there was a positive correlation of Dkk-3 and ECM-1 in cancer stroma, and ECM1 gene expression correlated with increased relapse-free survival of prostate cancer patients, suggesting ECM-1 has a tumor-inhibitory function." (PMID 29858602, 2018). "DKK3 silencing increased the level of the cell-adhesion regulator TGF-β–induced protein (TGFBI) in stromal and epithelial cell-conditioned media, and recombinant TGFBI increased prostate cancer cell invasion." (PMID 29858602, 2018). "Since docetaxel is the standard chemotherapy drug used to treat castrate-resistant prostate cancer, it would be interesting to determine the effects of combining CRISPR-mediated activation of DKK3 with docetaxel and of restoring DKK3 expression in docetaxel-resistant prostate cancer cells." (PMID 29843383, 2018). "In addition, ectopic expression of Dkk-3 inhibits prostate cancer cell proliferation and invasion, and an adenoviral vector expressing Dkk-3, Ad-REIC, has shown promise as a therapy for prostate cancer in early stage trials." (PMID 29858602, 2018). "DKK3 silencing reduced the level of extracellular matrix protein-1 (ECM-1) in prostate stromal cell-conditioned media but increased it in epithelial cell-conditioned media, and recombinant ECM-1 inhibited TGFBI-induced prostate cancer cell invasion." (PMID 29858602, 2018). "The correlation of ECM-1 and Dkk-3 expression in WPMY-1 cells, ECM-1 inhibition of TGFBI-dependent prostate cancer cell invasion and the correlation of ECM1 and DKK3 expression with relapse-free survival, suggest that ECM-1 also participates in the Dkk-3 defense mechanism." (PMID 29858602, 2018). "Some of these also noted expression of Dkk-3 in prostate cancer stroma, but the relevance of stromal Dkk-3 to prostate cancer was not examined." (PMID 29858602, 2018). "DKK3 was reported to selectively activate the c-Jun-NH2-kinase in human prostate cancer cells, suggesting inhibition of the non-canonical Wnt pathway." (PMID 28969056, 2017). "Our aim was to investigate whether the interaction between canine REIC/Dkk-3 and SGTA affects AR signalling and might contribute to the development of new strategies in canine androgen-independent prostate cancer treatment." (PMID 28599655, 2017).
prostate carcinoma (continued). "In dogs, nearly all prostate cancers are androgen-independent, and thus, we expected that prostate cancer cell lines derived from dog e.g. DPC-1, ACe-1, and Leo may downregulate the expression of REIC/Dkk-3." (PMID 28599655, 2017). "We showed that cytoplasmic REIC/DKK-3 interferes with the dimerization of SGTA and abolishes the function of SGTA as a negative regulator of the AR, resulting in enhanced AR sensitivity in human prostate cancer cells." (PMID 26658102, 2016). "DKK3 overexpression has also been linked to increased apoptosis in human prostate cancer cells involving JNK activation, indicating DKK3 may regulate non-canonical Wnt signaling in this setting." (PMID 35204808, 2022). "For example, it is required for the Dkk-3 inhibition of TGF-β-dependent migration and invasion in PC3 metastatic prostate cancer cells, suggesting that this domain might be useful to block the tumor-promoting effects of TGF-β signaling in advanced prostate cancer." (PMID 36497305, 2022). "Further analysis regarding the mechanisms of the AR complex maturation via REIC/Dkk-3 and SGTA interaction in in vitro and in vivo experiments should contribute to the development of a novel strategy for the treatment of canine androgen-independent prostate cancer." (PMID 28599655, 2017). "However, for the lung cancer cell lines NCI-H661 and NCI-H640, the glioblastoma cell line GaMG and the prostate cancer cell line PC3, PAX6 knockdown by siRNA resulted in an increased Dkk3 expression, indicating that endogenous PAX6 repressed Dkk3 expression in these cancer cell lines." (PMID 25029272, 2014). "Notably, doxycycline-inducible expression of DKK3 in LNCaP prostate cancer cells reduced cell proliferation but did not alter β-catenin cytoplasmic levels or inhibit Wnt/β-catenin signaling, consistent with the fact that DKK3 does not bind to the Wnt co-receptors LRP5/6 or KREMEN." (PMID 35204808, 2022). "Furthermore, validation with GEPIA database revealed that DKK3 expression was also decreased in prostate cancer, which further demonstrated that LINC00261 might regulate DKK3 by binding to transcription factor GATA6, thus affecting the development of prostate cancer." (PMID 33013201, 2020). "In conclusion, our results are consistent with a negative feedback model that implicates Dkk-3 and TGF-β signaling in the regulation of epithelial–stromal interactions taking place during prostate cancer initiation and progression." (PMID 29858602, 2018). "With regard to the anti-oncogenic role of REIC/DKK-3, we found that the expression level of TCTEX-1 positively correlated with the incidence of apoptosis in PC3 human prostate cancer cells overexpressing REIC/DKK-3 (data not shown)." (PMID 26658102, 2016).
breast cancer (47 papers, 2008 to 2024). A primary or metastatic malignant neoplasm involving the breast. "Previous studies have shown that individuals with reduced DKK3 levels have a higher risk of developing breast cancer, ovarian cancer, malignant glioma, and pancreatic cancer." (PMID 38678874, 2024). "We also demonstrate that DKK3 promotes immune-mediated progression of proliferative tumors and is significantly associated with poor survival and immunosuppression in human breast cancers." (PMID 37847565, 2023). "Dkk3 has been regarded as a tumor suppressor, and the methylation of Dkk3 has been reported to be associated with poor prognosis in advanced gastric cancers and breast cancers." (PMID 36923312, 2022). "Reduced DKK3 expression has been associated with endometrial cancer, cervical cancer and breast cancer, and as such it has been implicated as a tumor suppressor." (PMID 32854182, 2020). "In the present study we performed a comprehensive subtype-specific expression analysis of DKK3 in human breast cancer for the first time revealing pronounced loss of DKK3 in basal-type breast carcinomas." (PMID 27467270, 2016). "In an earlier study of our group we have already shown that DKK3 promoter-hypermethylation is associated with a poor prognosis (overall and disease free survival) in breast cancer patients." (PMID 27467270, 2016). "Breast cancer tissues showed a median DKK3 expression loss of 78% compared to healthy breast tissues." (PMID 27467270, 2016). "Subsequently, loss of DKK3 expression mainly mediated by promoter-hypermethylation was demonstrated in the majority of tumor entities including breast cancer." (PMID 27467270, 2016). "Loss of DKK3 expression is particularly observed in basal breast cancer and seems to be involved in the tumorigenesis of this subtype." (PMID 27467270, 2016). "Dickkopf 3 (DKK3) has been associated with tumor suppression of various tumor entities including breast cancer." (PMID 27467270, 2016). "Study reported 2-fold reduced breast cancer risk in women with GG genotype as compared to AA genotype in case of DKK-3 gene SNP." (PMID 25945348, 2015). "The homozygosity of the minor allele in the DKK3 gene also provided modest protection against breast cancer (OR, 0.424; CI, 0.183–0.983; p = 0.04333)." (PMID 23516639, 2013). "No statistical significant association was observed for this SNP in the DKK3 gene with the age of on-set of breast cancers." (PMID 23516639, 2013). "As EMT is implicated in regulating stem cell properties, we further investigated the expression of some stem cell-associated markers in DKK3-transfected breast cancer cells." (PMID 23890219, 2013). "Most important, major differences between WIF1 and DKK3 methylation arise in their association with breast cancer patient survival." (PMID 19570204, 2009). "In a bivariate analysis, WIF1 methylation status in breast carcinomas was significantly associated with the DKK3 methylation status." (PMID 19570204, 2009). "Multivariate, DKK3 methylation in breast carcinoma represented an independent and strong risk factor for OS (HR: 14.4; 95% CI: 1.9 – 111.6; p = 0.011)." (PMID 19570204, 2009). "We further showed that a loss of DKK3 protein in breast carcinomas is also associated with DKK3 promoter methylation (p = 0.001) whereas protein expression is abundant in epithelial cells of the normal breast." (PMID 18826564, 2008). "As a continuous variable, a lower IRS in breast carcinoma was significantly associated with the presence of DKK3 promoter methylation (p = 0.001; Fisher's exact test)." (PMID 18826564, 2008). "The loss of DKK3 gene expression in cancer is frequently a consequence of gene promoter methylation, which varies between 14% in non-small cell lung cancer and 78% in breast cancer." (PMID 36497305, 2022). "Here, we could confirm DKK3 expression loss in breast cancer specimens both on the mRNA and protein level." (PMID 27467270, 2016).
breast cancer (continued). "Further studies decoding the underlying molecular mechanisms of DKK3-mediated effects may help to identify novel targeted therapies for this clinically highly relevant breast cancer subtype." (PMID 27467270, 2016). "We examined rs6485350 in DKK3 gene for its association with the risk of breast cancer." (PMID 23516639, 2013). "Results showed that DKK3 expression was restored in response to 5-aza-dC treatment, along with increased unmethylated promoter alleles, suggesting that promoter methylation is directly responsible for DKK3 down-regulation in breast cancer cells." (PMID 23890219, 2013). "As an example, DKK3 may be a prime candidate gene to be incorporated into diagnostic multimarker panels, for its aberrant methylation is specific to malignant cells in breast cancer." (PMID 19570204, 2009). "Our study adds important information to this aspect, because it so far remained unknown if methylation-mediated loss of DKK3 expression also occurred in primary breast cancer, and, if so, how many patients were affected by this epimutation." (PMID 18826564, 2008). "• REIC/Dkk-3 protein effectively suppresses breast cancer progression through an acceleration of PD-L1 degradation." (PMID 36869893, 2023). "In contrast, overexpressed lncRNA MICAL2-1 was found to impair the migration and invasion of breast cancer cells by modulating the miR-25/DKK3 axis." (PMID 36613528, 2022). "Their results showed a significant association of genetic variants including AXIN2 rs3923087, β-catenin rs4135385, DKK3 rs6485350, SFRP3 rs7775 and TCF7L2 rs12255372 with breast cancer risk in the population." (PMID 34452579, 2021). "For instance, DKK3 and WIF1 methylation was detected in a similar proportion of breast cancer patients, but only DKK3 methylation was a prognostic marker of survival." (PMID 32083079, 2020). "In fact, increasing evidence has shown that the expression level of DKK3 is decreased in several human solid cancers, including prostate, colon, and breast cancers." (PMID 31423109, 2019). "Disruptive expression of DKK3 in cancers has been verified in some cancer types, including pancreatic cancer, renal cell carcinoma, thyroid cancer, breast cancer, and colorectal cancer, and downregulated expression of DKK3 has been observed." (PMID 31423109, 2019). "DKK3 protein levels in breast cancer (BC) stroma were significantly increased upon progression to more aggressive cancers, particularly in ER-negative BC." (PMID 30631061, 2019). "Using semi-quantitative real-time PCR, the DKK3 mRNA expression in 30 subtype-stratified breast cancer and 11 healthy breast tissue samples was analyzed." (PMID 27467270, 2016). "But a divergent DKK3 expression in the distinct breast cancer subtypes as well as a potential clinical impact for DKK3 only in basal and luminal tumors suggested a potential subtype-specific function of DKK3 in the development of human breast cancer." (PMID 27467270, 2016). "Based on three independent tissue cohorts including one in silico dataset (n = 30, n = 463 and n = 791) we observed a clear down-regulation of DKK3 expression in breast cancer samples compared to healthy breast tissue controls on mRNA and protein level." (PMID 27467270, 2016). "In an earlier study of our group, we have already shown that DKK3 expression is lost in human breast cancer by promoter-hypermethylation." (PMID 27467270, 2016). "DKK3 downregulated by shRNA (short hairpin RNA) led to an obvious increase in β-catenin/TCF-dependent gene activity in breast cancer cells." (PMID 27801786, 2016). "None of these reports focused on investigations of a possible subtype-specific function of DKK3 in the tumorigenesis of breast cancer." (PMID 27467270, 2016). "Stratifying the breast cancer cohort further by subtype revealed a potential prognostic relevance of DKK3 mRNA expression in tumors of the basal (P < 0.001) as well as the luminal subtype (P < 0.001) but not in HER2-positive carcinomas." (PMID 27467270, 2016).